TNF (tumor necrosis factor)
Diseases named in the same sentence as TNF in open-access papers (continued):
Sharing a sentence is not in itself a finding about the gene and the disease.
schizophrenia (continued). "TNF-α levels were significantly positively associated with PANSS negative symptoms in first-episode drug-naïve patients with schizophrenia, and were negatively correlated with the general psychopathology subscales and PANSS total scores in chronic patients with schizophrenia." (PMID 37189796, 2023). "In a 2015 study on 30 patients with schizophrenia, IL-6 and TNF-α levels were significantly elevated in the patient group treated with antipsychotics; this study also showed an immunological response in schizophrenia, despite the lack of factors that cause inflammation." (PMID 37644489, 2023). "Furthermore, in the same experimental conditions, we measured the expression levels of the main pro−inflammatory cytokines regulated by NF−kB (i.e., IL6, TNFα, and IL1β), given their proven role in the etiopathogenesis of several psychiatric diseases, including schizophrenia." (PMID 37240042, 2023). "Moreover, the expression levels of serum TNF-α and iNOS may be used as potential biomarkers for evaluating the condition of schizophrenia." (PMID 36246695, 2022). "Signs of a peripheral inflammatory response in schizophrenia are indicated by elevated serum/plasma levels of certain pro-inflammatory factors, including prostaglandin E2 and C-reactive protein, as well as some pro-inflammatory cytokines, such as IL-1β, IL-6, IL-8, and tumor necrosis factor-α." (PMID 35722585, 2022). "However, in patients with chronic schizophrenia, a negative association between the TNF-α levels and psychopathological symptoms has been reported." (PMID 34763685, 2021). "However, the interaction of TNF-α and OxS on the susceptibility and clinical characteristics of schizophrenia has not been investigated well." (PMID 34526062, 2021). "However, there were differences in the TNF levels in patients with schizophrenia after treatment." (PMID 34763685, 2021). "TNF-α may be an indicator of the immune dysfunction associated with negative symptoms of schizophrenia." (PMID 34763685, 2021). "For example, serum TNF-α levels may be a biomarker for application of hUC-MSC in schizophrenia." (PMID 32341334, 2020). "Importantly, IL-6 and TNFα, cytokines having novel roles in CNS development and functions including neuronal plasticity, cognition, and behavior, have been investigated quite extensively in schizophrenia." (PMID 30627222, 2018). "Thus schizophrenia patients taking haloperidol may be protected from RA onset by the suppression of TNF‐α and IL1‐β levels." (PMID 25656077, 2015). "Interestingly, some cytokines [IL-12, IFN-γ, TNF-α, soluble IL-2 receptor (sIL-2R)] may be trait markers for schizophrenia, while others are raised during phases of intensified symptoms (IL-1β, IL-6, and TGF-β)." (PMID 24550848, 2014). "Thus, TNF-α might be involved in the process of neurodevelopment and neurodegeneration, which could link to the pathogenesis of Schizophrenia by subtle alterations in neuronal number and density." (PMID 19506720, 2008). "Moreover, these bacteria produce pro-inflammatory molecules, such as lipopolysaccharides and pro-inflammatory cytokines, including IL-6 and TNF-α, which may exacerbate the processes previously discussed in relation to both schizophrenia and glucose homeostasis." (PMID 40426670, 2025). "Altered expression of several miRNAs, including those modulating IL-6 and tumor necrosis factor alpha (TNF-α) signaling, has been reported in recent-onset schizophrenia." (PMID 41302331, 2025). "Research indicated that schizophrenia and MDD patients had higher levels of IL-6, TNF-α, and IL-1β as compared to healthy controls." (PMID 40416228, 2025). "High serum levels of interleukin 1β (IL-1β), IL-6, or tumor necrosis factor-α (TNF-α), often manifested during acute relapse of schizophrenia, are significantly reduced by antipsychotic therapy." (PMID 41010622, 2025).
schizophrenia (continued). "Cytokine levels and different inflammatory mediators, such as tumor necrosis factor-alpha (TNF-α) and interleukin-6 (IL-6), are elevated in the peripheral blood of people diagnosed with schizophrenia." (PMID 40612741, 2025). "For instance, SNPs of genes encoding major proinflammatory and anti-inflammatory cytokines, including interleukins (IL) IL1-β, IL-6, IL-6R, IL-10, IL-17A, and tumor necrosis factor α (TNF-α), are related to schizophrenia." (PMID 40416497, 2025). "This study demonstrated that schizophrenia and MDD were inflammatory disorders because enhanced IL-6, TNF-α, and IL-1β levels showed direct links to symptom intensity in affected patients." (PMID 40416228, 2025). "Our study is consistent with previous findings that serum TNF-α levels were elevated in patients with CMS, suggesting a relationship between neuroinflammation and schizophrenia." (PMID 38429778, 2024). "Our study examined first episode patients with schizophrenia (FEPS), and the findings that TNF-α levels were higher in these patients than those in healthy controls were consistent with previous researches." (PMID 38956509, 2024). "Patients with schizophrenia and first episode psychosis (FEP) display abnormal profiles of proinflammatory cytokines (especially IL-6 and TNF-α) prior to start of treatment." (PMID 38177535, 2024). "Various ILs, type I IFNs, and tumor necrosis factor (TNF), inflammatory cytokines that have already been analyzed for their correlation with schizophrenia, are being expressed after TLR2 signals." (PMID 37376644, 2023). "Cytokine levels including IL-2, IL-4, IL-6, IL-10, TNF-α, and IFN-γ were tested, and we found significantly higher levels of IL-6 in patients with schizophrenia (P < 0.01)." (PMID 38066312, 2023). "IL-1β, IL-2, IL-4, IL-6, BAFF, IFN-α, GM-CSF, NRG1-β1, and GDNF increased but TNF-α and NGF-β decreased in schizophrenia compared to healthy individuals." (PMID 37239308, 2023). "We found that pro-inflammatory cytokines IL-6, TNF-α and IFN-γ had the greatest influence (relative to other cytokines) in a network involving a large set of both pro- and anti-cytokines in schizophrenia." (PMID 37723153, 2023). "We report that IL-6, TNF-α and IFN-γ had the greatest influence in a network of cytokines in individuals with schizophrenia." (PMID 37723153, 2023). "To explore this, we measured suPAR, CRP, TNF, sTNFR1 and IL-6 in plasma obtained before and after a 12-week exercise intervention RCT in individuals with schizophrenia." (PMID 37265560, 2023). "The signs of activation of Th2 immune response in schizophrenia include the increase of the IL-4 and IL-10 levels in blood serum, decrease of Th1/Th2 cytokine level ratio (IFN-γ/IL-4, IFN-γ/IL-10, IL-2/IL-4, TNF-α/IL-4)." (PMID 39944368, 2023). "For example, blood and cerebrospinal fluid concentrations of pro-inflammatory cytokines, including interleukin (IL)-6, IL-8, interferon gamma (IFNγ), tumor necrosis factor alpha (TNF-α), and others, are increased in schizophrenia." (PMID 37239308, 2023). "The cytokines that change in schizophrenia have similar changes in metabolic disorders, such as interleukin-1Rα(IL-1Rα), IL-1β, IL-2, IL-6, IL-10, interferon-γ(IFN-γ), tumor necrosis factor-α(TNF-α), and C-reactive protein (CRP)." (PMID 35135531, 2022). "In this work, we found significantly higher serum levels of proinflammatory (IFN-γ, IL-5, IL-6, IL-8, IL-15, and TNF-α) and anti-inflammatory (TGF-α, IL-10, and IL-1RA) cytokines in patients with schizophrenia than in healthy individuals." (PMID 36556337, 2022). "A meta-analysis showed increased levels of IL-6, IL-8, IL-10, IL-12, IL-1β, IFN-γ, TNF-α, and TGF-β in the blood of patients with schizophrenia, which was similar to our findings." (PMID 35223927, 2022). "It is reported that schizophrenia patients with a first-episode psychosis were observed to have increased blood concentrations of IL-1β, IL-6, IL-12, IFN-ɣ, TNF-α, TGF-β and sIL-2R compared to healthy controls." (PMID 34589729, 2021).
schizophrenia (continued). "Chronic patients with schizophrenia had lower TNF-α levels than normal controls, but another study showed that the TNF-α levels were significantly higher in chronic patients than in healthy controls." (PMID 34763685, 2021). "In this study of patients with first-episode schizophrenia and relatively well-matched controls, significant positive correlations between IDO levels and TNF-α and INF-γ levels were observed." (PMID 34802039, 2021). "Another study found that the TNF-α levels in chronic patients were positively related to PANSS negative symptoms, especially when the classification of deficit schizophrenia was employed." (PMID 34763685, 2021). "Significantly elevated levels of macrophage-derived cytokines IL-1β, IL-6, and TNF-α, as well as the Th1-derived cytokine IFN-γ support the macrophage-T-lymphocyte theory of schizophrenia pathophysiology." (PMID 34199832, 2021). "Increased levels of IL-6, IFN-γ, TNF-α, and TGF-β were also noted in acute relapsed schizophrenia inpatients (AR)." (PMID 34199832, 2021). "The correlation table showed the relationships between the Kyn pathway metabolites and the cytokines (TNF-α, IL-6), hsCRP, and BDNF in the schizophrenia group and the healthy control group." (PMID 34393855, 2021). "To this end, we focused on a panel of plasma cytokines (IL-1β, IL-6, IL-10, TNF-α, and IFN-γ), which have been used previously to assess signs of peripheral inflammation in major psychiatric disorders such as schizophrenia and animal models of MIA." (PMID 33230204, 2021). "We also evaluated the serum levels of cytokines (TNF-α, IL-6), hsCRP, and BDNF in patients with schizophrenia and healthy controls." (PMID 34393855, 2021). "There was a significant increase in the levels of TNFα, IL-1β, and IL-6 and a decrease in the levels of IFN-γ in patients with schizophrenia." (PMID 33552387, 2021). "This study aimed to investigate the differences in TNF-α levels and clinical correlations in first-episode drug-naïve (FEDN) patients with schizophrenia before and after treatment and in chronic patients." (PMID 34763685, 2021). "Our results demonstrate the sex difference in the relationship between TNF-α, MDA, and their interaction with psychopathological symptoms of patients with schizophrenia." (PMID 34526062, 2021). "The results showed a correlation between higher TNF-α values and augmented QUIN concentrations in schizophrenia." (PMID 32061259, 2020). "In all patients with schizophrenia, our results showed that plasma levels of SIRT1 were negatively correlated with IL-6 (r = −0.345, P = 0.011), IL-10 (r = −0.276, P = 0.043), and TNF-α (r = −0.393, P = 0.003)." (PMID 33324265, 2020). "Regarding studies with only CSF samples, correlations between IL-8 and QUIN, TNF-α and QUIN, and IL-6 and KYNA production were also found in schizophrenia." (PMID 32061259, 2020). "A meta-analysis reported that pro-inflammatory cytokines, including interleukin (IL)-1β, IL-6, and tumor necrosis factor (TNF)-ɑ, were elevated in the peripheral blood of schizophrenia patients." (PMID 32341334, 2020). "As CRP is produced by the liver when stimulated by cytokines such as TNF-α, these studies are in line with our finding of increased TNF-α levels in agitated patients with schizophrenia as well as in the general acute psychiatric population." (PMID 31509578, 2019). "Meta-analyses have shown that inflammatory markers such as tumor necrosis factor α (TNF-α) and C-reactive protein (CRP) are elevated in both schizophrenia and bipolar disorder." (PMID 28039552, 2017). "In keeping with our findings a meta-analysis of serum cytokine alterations in schizophrenia or related psychotic disorder patients found increased levels of interleukin, among those IL6, IL12, TNF-α, TGF-β although with significant heterogeneity." (PMID 27650124, 2016). "Dysregulation of TNF-α production may causes negative symptoms of psychosis and schizophrenia." (PMID 28117656, 2016).
schizophrenia (continued). "The positive association in the present study could be of significance as TNF-α has been demonstrated to have cytotoxic effects on embryonic mesencephalic dopaminergic neurons, which are suggested to have an important role in the etiopathogenesis of schizophrenia." (PMID 27177030, 2016). "The negative correlation between TNF-α and the prefrontal cortex in schizophrenia suggests a potential role for inflammation in the pathology of this brain region." (PMID 42254729, 2026). "Indeed, we used two-step recursive cluster analysis to define a high inflammatory biotype of ~46% of schizophrenia cases based on elevated pro-inflammatory transcripts (SERPINA3, IL6, IL1β, TNFα) in the midbrain across two independent cohorts." (PMID 40335479, 2025). "Shreds of evidence from preclinical and clinical studies have shown persistent elevation in various inflammatory markers like TNF-α, IL-12, IL-1β, IL-6, IL-1, and interferon (IFN)-γ in first onset and acute relapse schizophrenia subjects who were on antipsychotic medications." (PMID 39907868, 2025). "In schizophrenia, immune activation upregulates pro-inflammatory cytokines (e.g., IFN-γ, IL-1, TNF-α), which activate indoleamine 2,3-dioxygenase (IDO) via both IFN-γ receptor (IFN-γR)-dependent and independent pathways (e.g., synergistic action of TLR4, IL-1R, TNF-αR)." (PMID 41346597, 2025). "The aim of this study was to investigate the levels of tumor necrosis factor (TNF) and matrix metalloproteinase-2 (MMP-2) in male patients with treatment-resistant schizophrenia (TRS) and chronic medicated schizophrenia (CMS), and the relationship with psychopathology." (PMID 38429778, 2024). "Second, a negative correlation was also found between blood levels of TNF-α and the severity of treatment-resistant schizophrenia patients." (PMID 38586283, 2024). "Increased levels of pro-inflammatory cytokines such as interleukin (IL)-1β and tumor necrosis factor (TNF)-α have been found in the cerebrospinal fluid of schizophrenia patients, particularly those with negative symptoms." (PMID 39716387, 2024). "This adds further to the suggestion that targeting IL-6 may weaken a pro-inflammatory state and influential pro-inflammatory cytokines IL-6, TNF-α and IFN-γ might represent important biomarkers, and key targets for immune-based therapies in schizophrenia." (PMID 37723153, 2023). "Some signs of inflammation, such as IL-6 and TNF-α, overlap in both MDD and schizophrenia." (PMID 37280213, 2023). "In schizophrenia, neuroinflammation denotes the initiation of the brain’s immune response, which is principally driven by microglial cells and the discharge of inflammatory cytokines like IL-2, IL-4, IL-13 IFN-γ, and TNF-α." (PMID 38256307, 2023). "The finding that pro-inflammatory cytokines IL-6, TNF-α and IFN-γ had the greatest influence in the network is consistent with previous research that has demonstrated elevated mean levels of pro-inflammatory cytokines in individuals with schizophrenia." (PMID 37723153, 2023). "Here, we analyzed changes in serum concentrations of cytokines (IL-1β, IL-2, IL-4, IL-6, IL-10, IL-21, APRIL, BAFF, PBEF/Visfatin, IFN-α, and TNF-α) and growth/neurotrophic factors (GM-CSF, NRG1-β1, NGF-β, and GDNF) in patients with schizophrenia in an exacerbation phase." (PMID 37239308, 2023). "The presence of abnormally high levels of pro-inflammatory cytokines such as Tumor Necrosis Factor alpha (TNF-α) and Interleukin 6 (IL-6) found in schizophrenia patients indicates that in some patients it is possible that the immune system balance is being tipped toward a more inflammatory state." (PMID 35844244, 2022). "Most importantly, during inflammatory responses, IL-22 is upregulated in the brain and may increase the production of TNF-α, IL-6, and prostaglandins and induce STAT3, MAP-kinase, and JAK-STAT pathways, which all play a role in schizophrenia." (PMID 36256663, 2022).
schizophrenia (continued). "Some research on patients with schizophrenia indicates statistically significantly greater IL-1β, IL-8, IL-17, IL-23, and TNF-α levels in women but not in men, compared with healthy individuals." (PMID 36556337, 2022). "A significant positive correlation was found between the serum levels of TNF-α and Kyn (r = 0.53, p = 0.0026) and the Kyn/tryptophan (Trp) value (r = 0.67, p = 0.000046) in the schizophrenia group, but not in the healthy control group." (PMID 34393855, 2021). "A number of studies among patients with first episode and persistent or recurrent schizophrenia have shown increased serum levels of acute phase proteins, such as CRP, and proinflammatory markers such as tumor necrosis factor (TNF-alpha), IL-6, and IL-1β, although with some inconsistency." (PMID 34465310, 2021). "In our study there was no significant increase of TNFα among patients with episodic or continuous schizophrenia, although IL-8 was increased." (PMID 38601098, 2021). "Studies on plasma cytokines levels have reported elevated levels of major inflammatory cytokines such as IL-1β, TNF-α, and INF-γ; low-grade systemic inflammation has been shown to be present in first-episode psychosis (FEP) and pre-onset state of schizophrenia." (PMID 33815179, 2021). "Of other notable signatures relevant to immune signaling, the “inflammatory response” satisfied a less stringent FDR < 0.25 but not <0.05, and the “IL-6 JAK-STAT3 signaling” and “TNF-α signaling via NF-κB” signatures were not enriched in schizophrenia." (PMID 34054608, 2021). "We previously reported that the interaction between TNF-α and MDA increased the risk for the occurrence of schizophrenia by 1.61 times, but no significant interactive effects were found on any domain of the PANSS." (PMID 34526062, 2021). "TNF-α and IL-6 were associated with the deficit syndrome, and TNF-α predicted blunted affect, alogia, and total negative symptoms in schizophrenia patients." (PMID 34199832, 2021). "Similarly, TNF-α increases have been observed in several neuropsychiatric disorders, including MDD, BD, and schizophrenia, and potentially contributes to the neuropathology of these disorders." (PMID 33854417, 2021). "It has been suggested that HERVs reactivation may be mediated by NF-κB with the involvement of TNF-α and INF-γ, whose peripheral levels are elevated in schizophrenia." (PMID 34501305, 2021). "Serum levels of TNF-α in the schizophrenia group were not different from those in the healthy control group in the present study." (PMID 34393855, 2021). "Numerous studies have demonstrated that TNF-α and TNF-α-related signaling pathways may be crucial in the pathophysiological mechanisms of schizophrenia." (PMID 34763685, 2021). "No sex difference was found in the TNF-α levels in the patients with schizophrenia in our study, which is consistent with the findings of one study." (PMID 34763685, 2021). "This suggests that androgen may have complex interactions with the immune system and OxS, which may explain the reasons for the interaction existence between TNF-α and MDA only in male FEDN schizophrenia patients." (PMID 34526062, 2021). "In contrast to the initial findings, we did not observe any changes for IL-6, TNFα and glucose in schizophrenia, nor for BDNF and IL-6 in MDD." (PMID 33653423, 2021). "Conversely, another study found that the TNF-α levels were positively related to PANSS negative symptoms in chronic deficit patients with schizophrenia." (PMID 34763685, 2021). "Our findings showed a significant positive correlation between the serum levels of TNF-α and the Kyn levels and the Kyn/Trp value in the schizophrenia group, but not in the healthy control group." (PMID 34393855, 2021). "We measured in 46 patients with schizophrenia and MetS serum levels of adiponectin insulin, leptin, TNF-α and IL-6 and compared these levels to those of patients with schizophrenia without MetS." (PMID 33066473, 2020).